SAV1 (salvador family WW domain containing protein 1)
Diseases named in the same sentence as SAV1 in open-access papers (continued):
Sharing a sentence is not in itself a finding about the gene and the disease.
tumor (60 papers, 2011 to 2026). "The expression level of SAV1 was significantly decreased in GC tissues and cell lines, negatively associated with tumor invasion depth, lymph node metastasis, and TNM stage, and positively associated with the overall survival of patients with GC." (PMID 37033161, 2023). "Decreased SAV1 expression was positively associated with tumor invasion depth (T stage), lymph node metastasis (N stage), and TNM stages." (PMID 37033161, 2023). "The decreased immunoreactivity of SAV1 in the tumor specimens was associated with lymph node involvement (N0 vs. N1 + N2, p = 0.0022) and higher TNM disease stage (I + II vs. III + IV, p = 0.0034) and histological grade (G2 vs. G3, p = 0.0489)." (PMID 38136317, 2023). "Our current understanding of the pathway in chicken is focused on SAV1 gene, encoding protein SAV1 known to be a tumor suppressor in mammals and Drosophila, acts as a core partner of the Ser/Thr protein kinase MSTs (MST1 and MST2)." (PMID 27505353, 2016). "The co-occurrence of marked oval cell expansion and mixed HCCs/CCs in the Sav1-deficient mice suggests the tumours arise from transformed oval cells that retain some capacity for hepatocytic and cholangiocytic differentiation." (PMID 21102585, 2011). "NDRG1 contributes to tumor aggressiveness by cell proliferation and lipid metabolism regulation, whereas GAPVD1, INPP5A, TCN1, SAV1, RBBP8, SPIB, and UBE2A also exhibit oncogenic or tumor-suppressive properties associated with prognosis." (PMID 41511940, 2026). "On the other hand, AYAP expression was more prominent in normal compared to tumor tissue, while SAV1 was the only marker showing strong staining in both normal and neoplastic tissue." (PMID 40649713, 2025). "SAV1 mainly acts as a scaffold in the tumour-suppressor Hippo pathway that regulates cell proliferation and cell death and is one of the key signal pathways that controls carcinogenesis." (PMID 41303597, 2025). "The tumor suppressor SAV1 is downregulated in various tumor types, leading to tumor invasion, disease progression, and ultimately poor prognosis." (PMID 40141028, 2025). "The Hippo pathway consists of four tumor suppressors: SAV1, MST1/2, LATS1/2, and MOB kinase activators." (PMID 38920690, 2024). "Salvador homologue 1 (SAV1), which is reported to act as a tumor suppressor in different types of cancer, is one of the key components of the Hippo pathway." (PMID 37033161, 2023). "High-grade ccRCC is associated with the downregulation of salvador homolog 1 (SAV1), which is a tumor suppressor and a component of the Hippo signaling pathway." (PMID 37190141, 2023). "A decreased SAV1 protein immunoreactivity in the tumor samples was associated with lymph node involvement and higher TNM disease stage and histological grade, confirming the tumor-suppressive role of SAV1." (PMID 38136317, 2023). "Collectively, these data demonstrated that SAV1 served as a tumor suppressor by inhibiting the proliferation, migration, and invasion of GC cells." (PMID 37033161, 2023). "SAV1 expression in cancer tissues was much lower than that in tumor-adjacent normal gastric tissues." (PMID 37033161, 2023). "Collectively, these findings demonstrated that SAV1 suppressed the proliferation, migration, and invasion of GC cells and also functioned as a tumor suppressor in GC." (PMID 37033161, 2023). "As a consequence, the xenograft tumor formation ability was decreased in the SAV1-overexpressed group." (PMID 35864957, 2022). "Using this model, we found that SAV1 overexpression inhibited tumor growth compared to the control and was more profound in the smoking group." (PMID 35864957, 2022). "While ALKBH5-overexpression and SAV1-silencing group showed significantly delayed tumor growth and progression." (PMID 35414790, 2022). "Studies have shown that human Salvador homolog 1 (SAV1), as a component of the Hippo signaling pathway, is downregulated in high-grade ccRCC, which is known to be a tumor suppressor in Drosophila." (PMID 36483738, 2022).
tumor (continued). "The Hippo pathway comprises several tumor suppressors, including Mst1/2, Sav1/WW45, Lats1/2, and Mob1, which act as kinases that phosphorylate and inactivate of YAP." (PMID 32219176, 2020). "SAV1 has long been regarded as an adaptor protein in the Hippo pathway, but has not been well-studied, although emerging evidence indicates that SAV1 is essential for tumor suppression." (PMID 32439835, 2020). "In contrast, SAV1 overexpression by transfecting cancer cells with SAV1 cDNA–plasmid inhibits tumorigenesis and improves survival of tumor-bearing mice." (PMID 32439835, 2020). "The core upstream components of the Hippo pathway comprise several tumour suppressors, including Mst1/2, Sav1/WW45, Lats1/2, and Mob122." (PMID 32661222, 2020). "Immunohistochemical (IHC) staining showed that SAV1 expression levels were significantly higher in the tumor samples from the lycorine-treated xenograft mice compared with those of the PBS controls." (PMID 32439835, 2020). "Strikingly, treating tumor-bearing xenograft mice with lycorine increased SAV1 levels, and strongly inhibited tumor growth, vasculogenic mimicry, and metastasis." (PMID 32439835, 2020). "Our preliminary experiments of gene expression profile using reverse transcription polymerase chain reaction (RT-PCR) and western blotting showed that lycorine promoted SAV1 expression in the tumors of tumor-bearing mice." (PMID 32439835, 2020). "Salvador homolog-1 (SAV1) is a tumor suppressor required for activation of the tumor-suppressive Hippo pathway and inhibition of tumorigenesis." (PMID 32439835, 2020). "This oncogenic function of YAP1 is further supported by tumor suppressors such as Mst1/2 and Sav1 which inhibit YAP1 activity by phosphorylation." (PMID 31731480, 2019). "The protein levels of Rassf1, Mst1, Mst2, Sav1, Mob1, and p-Mob1 increased in the UA-treated xenograft tumor tissues as compared with those in the control tumor tissues." (PMID 31547587, 2019). "Tumors from Mst 1/2 double-KO and Sav1 KO mice clustered together as these genes are core regulator genes of the tumor suppressive Hippo pathway." (PMID 31731480, 2019). "The highly conserved SAV1 protein, also referred to as WW45, has been identified as a tumor suppressor in human cancer, acting as a cofactor/adaptor/regulator of the MST kinases and promoting Hippo signaling." (PMID 29673168, 2018). "To reveal the physiological role of this negative feedback regulation, we deleted Lats2 or Lats1 in the liver-specific Sav1-knockout mouse model which develops a YAP-induced tumor." (PMID 27006470, 2016). "Further analysis of SAV1 function revealed that it is a putative tumor suppressor gene in high-grade ccRCCs." (PMID 22185343, 2011). "In tumor cells, SAV1 downregulation at the protein level was observed in 64 of the 98 ccRCC cases, and it was correlated with tumor grade." (PMID 22185343, 2011). "We found that the SAV1 gene, a human homolog of salvador, which is known to be a tumor suppressor in Drosophila, was significantly downregulated in ccRCCs with 14q loss." (PMID 22185343, 2011). "Additionally, NaB treatment resulted in a marked elevation in the expression of SAV1, a tumor-suppressor gene involved in the Hippo pathway." (PMID 40872562, 2025). "Of the 94 tumor tissue samples studied, the relative immunoreactivity of SAV1 was reduced in 11 (11.7%) and increased in 59 (62.8%) cases, while 24 (25.5%) tumor specimens showed similar levels of SAV1 immunoreactivity to their corresponding non-cancerous tissues cells." (PMID 38136317, 2023). "Further, we sought to understand the cellular function of SAV1 in tumor invasion and metastasis." (PMID 35864957, 2022). "Loss-of-function of the tumor suppressors (MST1/2, LATS1/2, SAV1 etc.)and activation of transcriptional coactivators YAP/TAZ (caused by protein overexpression and/or enhanced nuclear accumulation) play important roles in tumorigenesis and cancer-associated malignant features." (PMID 33467099, 2021).
tumor (continued). "Thus, SAV1 plays a crucial role in tumor suppression via Hippo pathway-dependent and -independent mechanisms." (PMID 32439835, 2020). "RAS bound with RASSF5, activate MST1/235,44 to form STK3/MST2 and STK4/MST1 complexes in the hippo signaling pathway that plays a crucial role in tumor suppression by limiting proliferation and stimulating apoptosis where SAV1, MOB1A/B act as effector molecules." (PMID 32884013, 2020). "The core upstream components of this pathway comprise several tumor suppressors, including Mst1/2, Sav1/WW45, Lats1/2, and Mob1, which act in a kinase cascade that culminate in the phosphorylation and inactivation of YAP/TAZ (transcriptional co-activator with PDZ-binding motif)." (PMID 29449645, 2018). "The transcriptional coactivator YAP is a major downstream negative effector of the Hippo pathway 6, 7 and is tightly negatively regulated by a series of upstream components such as NF2, LATS1/2, MST1/2 and SAV1, which are tumour suppressors in several types of human cancers." (PMID 28470935, 2017). "The liver of Alb–cre Sav1 null mice show a progressive increase in Yap polypeptide greater than that seen in Mst1/Mst2 null livers, with highest levels present in the Sav1 null liver tumours." (PMID 21102585, 2011). "Although the average SAV1 immunoreactivity was increased in the CRC samples compared to the non-cancerous tissues, a decreased immunoreactivity of the SAV1 protein in the tumor specimens was associated with lymph node involvement and higher TNM disease stage and histological grade." (PMID 38136317, 2023). "The Hippo signaling pathway is a highly conserved tumor suppressor pathway, mainly including Ste20-like kinase 1 (MST1) and large tumor suppressor 1 (LATS1), Yes associated protein 1 (YAP1) and its analog TAZ, and the regulatory subunits of MST1 and LATS1, MOB1 and SAV1." (PMID 35810157, 2022). "To recapitulate the tumorigenic phenotype shown in the mouse model in which negative feedback on YAP/TAZ is ablated, we characterized tumor-associated cellular phenotypes in the AML-12 normal mouse liver cell line after depletion of SAV1, LATS1, and/or LATS2 proteins with shRNA constructs." (PMID 27006470, 2016). "Therefore, our present data appear to provide strong support for the hypothesis that the SAV1 gene may be a potential tumor suppressor of RCC." (PMID 22185343, 2011). "Furthermore, SAV1 has been reported to act as a tumor suppressor in cancers other than RCC." (PMID 22185343, 2011). "NaB increased YAP1 phosphorylation and decreased the transcription of CTGF and CYR-61 in HCT-116 cells, along with upregulation of SAV1 and downregulation of TAZ, suggesting partial reactivation of Hippo tumor suppressor functions." (PMID 40872562, 2025). "The four core components in this pathway, mammalian STE20-like protein kinase (MST1/2), Salvador homolog 1 (SAV1), MOB kinase activator 1A/B (MOB1), and large tumor suppressor kinase 1/2 (LATS1/2), all have tumor suppressive activity." (PMID 38893092, 2024). "The following four components, SAV1 (also known as WW45), MST1 and MST2 kinases, MOB1, and LATS1 and LATS2 kinases, have been demonstrated to function together as tumour suppressors." (PMID 37469419, 2023). "Under the condition of exogenous overexpression of SAV1, YAP-TEAD inhibitor (VP, Verteporfin) and hypomethylating agents (AZA, Azacytidine) were effective in constraining the tumor growth and the combination of the two drugs was significantly effective." (PMID 35864957, 2022). "SAV1 is an important component of the HIPPO pathway, which is highly conserved in mammals and plays a crucial role in the development of neoplasms and stem cell fate regulation." (PMID 35414790, 2022). "As shown, SAV1 and TSPAN14 are more strongly stained in the tumor specimens, and there are kinds of literature showing that their expression profiles are confirmed to be related to BRCA." (PMID 34930307, 2021).
tumor (continued). "We also show that activation of the Hippo pathway blocks tumor growth through inhibition of the oncoprotein YAP and uncover tumor regulatory functions for Hippo pathway members (SAV1 and FRMD6)." (PMID 34031411, 2021). "The protein expression profiles of the three genes, i.e., ADRB1, SAV1 and TSPAN14, involved in the PRS model demonstrated that the latter two genes are more strongly stained in tumor specimens." (PMID 34930307, 2021). "From these results, we found that transcript expression of SAV1 was downregulated by 1.65-fold (p = 0.003), LATS2 by 1.95-fold (p = 0.010) and YAP1 by 1.4-fold (p = 0.007) in tumor samples compared with CC samples." (PMID 32218280, 2020). "To further test these findings, we used two different methods to measure SAV1 and YAP expression in the tumor samples." (PMID 32439835, 2020). "The four core components in this pathway comprise MST1 and MST2 kinases, SAV1 (also termed WW45), MOB1, and LATS1 and LATS2 kinases, all of which have been shown to act as tumor suppressors." (PMID 29565815, 2018). "Instead, SAV1 SARAH and MST2 SARAH form a heterodimer, similar to that formed by the SARAH domains of MST2 and one of the RASSF family of tumor suppressors, RASSF5." (PMID 29063833, 2017). "It is clear that SAV1 and LATS1/2 play essential roles in tumor suppression." (PMID 38920690, 2024). "In light of these studies, it was surprising for us to observe higher average SAV1 immunostaining in tumor tissues compared to non-cancerous tissues." (PMID 38136317, 2023). "One of the fundamental components of the Hippo pathway, SAV1 (also known as WW45), is a 45 kDa protein thought to be a tumor suppressor, but its clinical and prognostic significance in CRC is unknown." (PMID 38136317, 2023). "Among the 94 tumor samples studied, the relative level of SAV1 mRNA (tumor tissue vs. matched non-cancerous mucosa) was reduced in eighty-eight (93.6%) tumors, while it was elevated in six (6.4%) cases." (PMID 38136317, 2023). "The average level of SAV1 mRNA was decreased in 93.6% of the tumor tissues compared to the corresponding non-cancerous tissues and biopsies of healthy colon mucosa." (PMID 38136317, 2023). "The associations between the tumor purity and these 12 immune-survival-related genes were analyzed; the results revealed that four genes, i.e., FAM134B, ALDH3A2, SAV1, and RORC were positively related to tumor purity, and one gene (FN1) was negatively related to tumor purity." (PMID 35893817, 2022). "Knockout of YAP/TAZ and their TEAD cofactors inhibited HPAF-II tumor cell proliferation, whereas knockout of their negative regulators SAV1 and LATS1 promoted in vivo (but not in vitro) tumor growth." (PMID 35536676, 2022). "The elevated expressions of FAM134B; ALDH3A2; RORC; and SAV1 were related to superior MESO’s OS, indicating that only four tumor antigens could be assumed to stimulate the immune system." (PMID 35893817, 2022). "Third, SAV1 overexpression inhibits cancer cell proliferation and motility and induces tumor cell apoptosis without obvious side effects in tumor-bearing mice." (PMID 32439835, 2020). "In addition, in xenograft tumours, we also confirmed that the expression of LATS2 and SAV1 was upregulated in the group treated with miR-103a-3p antagomir compared with the control group." (PMID 33218358, 2020). "In addition, the protein levels of Rassf1, Mst1, Mst2, Sav1, Mob1, and p-Mob1 were increased, whereas those of YAP and CTGF were diminished in UA-treated xenograft tumor tissues." (PMID 31547587, 2019). "When we evaluated the correlation between nuclear localization of YAP1 and tumor grade, nuclear localization of YAP1 was preferentially detected in high-grade, suggesting that the suppression of Hippo signaling through SAV1 downregulation tends to occur in high-grade ccRCCs." (PMID 22185343, 2011).
tumor (continued). "A major repressor of YAP function is the tumor-suppressive Hippo pathway, which is represented by a serine/threonine kinase cascade in which the mammalian sterile 20-like kinase 1 or 2 (MST1 or MST2) binds and phosphorylates the scaffold protein Salvador homolog 1 (SAV1)." (PMID 41484057, 2026). "Similarly, SAV1 showed a stage-dependent expression pattern: all advanced-stage tumors exhibited uniform positivity of SAV1 in all tumor cells, whereas in 23.4% of early-stage tumors, tumor cell subpopulations lacked SAV1 expression." (PMID 40649713, 2025). "Therefore, it is not surprising that SAV1 has tumour-suppressive roles and that its low expression in cancer is associated with poor prognosis." (PMID 41303597, 2025). "Although our study showed that the average SAV1 immunoreactivity was increased in the CRC tissue compared to the non-cancerous large intestine tissue, we observed a reduced SAV1 protein immunoreactivity in the tumor tissues from the patients with worse clinicopathological parameters." (PMID 38136317, 2023). "The average SAV1 mRNA expression was significantly downregulated in the tumor specimens compared to that observed in the non-cancerous tissue of the CRC patients and the colonic mucosa of the healthy subjects (0.5 ± 0.03 vs. 1.25 ± 0.08 and 1.00 ± 0.03, respectively; p < 0.0001)." (PMID 38136317, 2023). "The analysis further revealed a total of tumor antigens including FAM134B, ALDH3A2, SAV1, RORC, and FN1, which were considered as significant candidates for the MESO-mRNA vaccine that could have immune provocative effects and be both presented and processed by APCs for a tumor response induction." (PMID 35893817, 2022). "A major regulator of YAP/TAZ activity is the tumor suppressive Hippo pathway, which consists of a serine/threonine kinase cascade comprised by the mammalian sterile 20-like kinase 1 or 2 (MST1 or MST2), which binds and phosphorylates the scaffold protein Salvador homolog 1 (SAV1)." (PMID 34680275, 2021). "Second, SAV1 induces the protein kinase-phosphorylation cascade (MST1/2-LAST1/2-YAP/TAZ) in the Hippo pathway and simultaneously inhibits several other tumorigenic signal pathways, such as the AKT and NF-κB signal pathways in cancer cells, therefore amplifying SAV1-mediated tumor suppression." (PMID 32439835, 2020). "SAV1 appears to be an important component for MERTK-inhibition triggered Akt inactivation, and the SAV1 expression status could be one marker of whether MERTK inhibitors, which are entering clinical trials, will be efficacious as anti-tumor cell-directed therapies." (PMID 30944303, 2019). "SAV1 immunohistochemical staining was observed in tumor cells in 66/94 (70.2%) of the CRC cases studied, whereas, in the epithelial cells of non-cancerous colorectal tissues, SAV1 immunostaining was seen in 43/94 (45.7%) cases." (PMID 38136317, 2023). "Further analysis of the correlation between SAV1 and YAP1 expression in 28 different tissues revealed that in 20 different tissues, the expression of SAV1 and YAP1 was significantly and positively correlated in normal tissues, but the positive correlation was not significant in tumor tissues." (PMID 35864957, 2022).